ICAM1 (intercellular adhesion molecule 1)
Diseases named in the same sentence as ICAM1 in open-access papers (continued):
Sharing a sentence is not in itself a finding about the gene and the disease.
Blau syndrome (1 paper, 2021). Blau syndrome (BS) is a rare systemic inflammatory disease characterized by early onset granulomatous arthritis, uveitis and skin rash. "In the granulomatous skin lesion of a Blau syndrome patient, ICAM-1 and PDGF-B were positively immunostained in NOD2-expressing giant cells." (PMID 33923123, 2021). "Diffuse ICAM-1 expression along the surface of MGC and PDGF-B expression within granuloma-forming epithelioid cells and MGC formation in a Blau syndrome patient’s skin specimen seem compatible with their predicted functions." (PMID 33923123, 2021). "Collectively, these observations suggest that sustained surface ICAM-1 expression on and transient PDGF-B production in newly differentiating macrophages that harbor a mutant NOD2 and respond to some stimuli might play a role in granuloma formation in Blau syndrome patients." (PMID 33923123, 2021).
blood disease (1 paper, 2024). A disease that occurs in the blood. "We also validated the expression level of ICAM-1 using data from the online database of blood diseases." (PMID 38971796, 2024).
blood pressure (1 paper, 2017). "Elevated blood pressure accelerates atherogenesis while angiotensin-II may independently promote vascular inflammation by increasing oxidative stress in vessel walls ICAM1 (inter-cellular adhesion molecule-1) was also up-regulated by IL-1α in other studies." (PMID 28323859, 2017).
Brain atrophy (1 paper, 2016). Partial or complete wasting (loss) of brain tissue that was once present. "The positive effect from fingolimod is due to reduction in lymphocytes, markers of inflammation [intercellular adhesion molecule-1 (ICAM-1), interferon-γ, and interleukin-17], apoptosis, and brain atrophy." (PMID 27917153, 2016).
brucellosis (1 paper, 2024). Brucellosis is a bacterial infection that spreads from animals to people via unpasteurized dairy products or by exposure to contaminated animal products or infected animals. "In our study, we observed elevated levels of endothelial injury markers, including von Willebrand factor (VWF), VCAM-1, and ICAM-1, in patients with acute and chronic Brucellosis." (PMID 39872944, 2024).
CADASIL (1 paper, 2023). "The profound increased expression of ICAM-1 and IL-6 in vitro in VSMCs also supports the hypothesis that there is a unique inflammatory response in many arterioles in CADASIL." (PMID 37158955, 2023).
cerebellar pilocytic astrocytoma (1 paper, 2013). A WHO Grade 1 astrocytoma which arises in the cerebellum. "Hypothalamo-chiasmatic pilocytic astrocytomas and cerebellar pilocytic astrocytomas have a distinctive gene signature and several differential expressed genes (ICAM1, CRK, CD36, and IQGAP1) are targets for available drugs: fluvastatin and/or celecoxib." (PMID 24252689, 2013).
cerebral lesions (1 paper, 2018). "Thus, the lower intensity of cerebral lesions observed in Ext-Ts-treated PbA-infected mice in our investigation was related to the lower IFN-γ and consequently lower ICAM-1 and VCAM-1 expression in the organ as well as the decrease of chemokine receptor CCR5 involved in leukocyte trafficking." (PMID 29367729, 2018).
cervical squamous cell carcinoma (1 paper, 2025). A squamous cell carcinoma arising from the cervical epithelium. "Furthermore, compared to normal cervical tissues, the protein expression of FN1, ICAM1, and PLAU was significantly upregulated in cervical squamous cell carcinomas." (PMID 40141137, 2025).
cervical tumors (1 paper, 2025). "ICAM1-positive SiHa cells were utilized to establish the standard and late-stage models of human cervical tumors in nude mice." (PMID 39971940, 2025). "We first performed the whole transcriptomic analysis of ICAM1-ADC treated cervical tumors from the late-stage tumor models via RNA-sequencing (RNA-seq)." (PMID 39971940, 2025). "Here we utilized I-Gd to non-invasively quantify tumoral antigen expression of ICAM1 in the CDX model of human cervical tumor (SiHa) via MRI." (PMID 39971940, 2025). "Next, we performed an IHC staining on the ICAM1 ADC-treated cervical tumors harvested from the late-stage model." (PMID 39971940, 2025). "Thus, this study evaluated the therapeutic potential of ICAM1-ADCs in both standard and late-stage cervical tumor models." (PMID 39971940, 2025). "The IHC staining of ICAM1 expression shows heterogeneous patterns in cervical tumor tissues." (PMID 39971940, 2025). "Importantly, the ICAM1 positive rate in cervical tumor tissues was determined as 24.32% (27/111)." (PMID 39971940, 2025). "The results indicate that the I-Gd MRI probe can accurately and noninvasively detect ICAM1-positive cervical tumors, providing a simple and noninvasive approach to screen patients with high ICAM1 expression and identify those who would benefit from ICAM1-ADC therapy." (PMID 39971940, 2025). "Additionally, to confirm that immune activation (such as the IFN signaling pathway) is indeed induced by I-DXd treatment rather than ICAM1 antibody, we analyzed the potential signaling transductions in human cervical tumors by ICAM1 neutralizing antibody using RNA transcriptomic analyses." (PMID 39971940, 2025).
Chagas cardiomyopathy (1 paper, 2015). A disease of the cardiac muscle developed subsequent to the initial protozoan infection by trypanosoma cruzi. "In Chagas cardiomyopathy, there is an inflammatory vasculopathy, which is demonstrated by sustained expression of the adhesion molecules E-selectin, VCAM-1 and ICAM-1 during T. cruzi infection." (PMID 25978361, 2015).
Chlamydia infection (1 paper, 2008). "Up-regulation of another adhesion molecule, namely intracellular cell adhesion molecule (ICAM-1), was observed in human umbilical vein endothelial cells upon Chlamydia infection." (PMID 18284660, 2008).
Chlamydia pneumonia (1 paper, 2016). "We measured high sensitivity C-reactive protein (hs-CRP), procalcitonin, E-selectin, intercellular adhesion molecule-1 (ICAM-1), serum level of immune complexes (IC), and identified antibodies against Herpes simplex virus type 1 (HSV), Cytomegalovirus, Chlamydia pneumonia, and Helicobacter pylori." (PMID 28051279, 2016).
chlamydial infection (1 paper, 2008). "ICAM-1 and VCAM-1 have been found to be significantly elevated in the vasculature after genital chlamydial infection in the murine model." (PMID 18974840, 2008).
choroidal melanoma (1 paper, 2008). Malignant tumor of melanocytes of the choroid. "ICAM-1 mRNA levels were higher in this mouse model of choroidal melanoma than in controls." (PMID 18958307, 2008).
chronic asthma (1 paper, 2022). An asthma that is characterized by the development of persistent airway inflammation and recurrent attacks of breathlessness and wheezing, which vary in severity and frequency. "Here, we believe that the induction of chronic asthma model in rats in a 70-day period led to significant pathological outcomes which is supported by the up-regulation of vascular adhesion molecules like ICAM-1 and VCAM-1 involved in cell orientation from blood into the lung parenchyma." (PMID 35209844, 2022).
chronic bronchitis (1 paper, 2013). A type of chronic obstructive pulmonary disease characterized by chronic inflammation in the bronchial tree that results in edema, mucus production, obstruction, and reduced airflow to and from the lung alveoli. "Increased ICAM-1 increases susceptibility to infection and ICAM-1 appears to be upregulated in the bronchial mucosa of patients with chronic bronchitis." (PMID 23945277, 2013).
chronic endometritis (1 paper, 2025). A non-granulomatous or granulomatous chronic inflammation of the endometrium. "Immunohistochemistry analysis further revealed elevated ICAM-1 expression in endometrial biopsies form patients with chronic endometritis." (PMID 41583494, 2025).
chronic hepatitis (1 paper, 2012). An active inflammatory process affecting the liver for more than six months. "We used HSECs treated with IFN-γ and TNF-α in flow-based adhesion assays to model inflamed HSEC, which express ICAM-1, VCAM-1, and CXCR3 ligands in chronic hepatitis." (PMID 22796894, 2012).
chronic hepatitis C (1 paper, 2021). "CD4+ or CD8+T cell microparticles were more abundant in the circulation of patients with chronic hepatitis C (CHC) while microparticles purified from Jurkat T cells utilized CD11a/CD18 to bind to HSC via cellular CD54 (ICAM-1)." (PMID 34202136, 2021).
Coats disease (1 paper, 2020). Coats disease (CD) is an idiopathic disorder characterized by retinal telangiectasia with deposition of intraretinal or subretinal exudates, potentially leading to retinal detachment and unilateral blindness. "We found that the concentrations of 8 out of 22 cytokines (VEGF, IL-6, IL-8, MCP-1, MIP-1α, IP-10, VACM-1 and ICAM-1) were significantly increased in the AH of eyes with Coats disease." (PMID 32370768, 2020). "Of the 22 measured cytokines, the concentrations of 8 cytokines (VEGF, IL-6, IL-8, MCP-1, MIP-1α, IP-10, VCAM-1 and ICAM-1) were significantly higher in the Coats disease group than in the control group (all P < 0.002)." (PMID 32370768, 2020). "In the present study, significantly elevated VCAM-1 and ICAM-1 provide a possible molecular evidence for increased vascular permeability and accumulation of inflammatory cells in Coats disease." (PMID 32370768, 2020). "The concentrations of 8 cytokines (VEGF, IL-6, IL-8, MCP-1, MIP-1α, IP-10, VCAM-1 and ICAM-1) were significantly higher in the Coats disease group than in the control group (all P < 0.002)." (PMID 32370768, 2020). "Various cytokines in the AH, including elevated VEGF, IL-6, IL-8, MCP-1, MIP-1α, IP-10, VCAM-1 and ICAM-1, may be involved in the pathogenesis and progression of Coats disease." (PMID 32370768, 2020).
congenital heart disease (1 paper, 2013). A heart disease that is present at birth. "In accordance with the present results showing a tight relation between pulmonary ICAM-1 expression and the PVR, the severity of the pulmonary hypertensive disease has been tightly correlated to serum level of soluble ICAM-1 in patients with congenital heart disease and PH." (PMID 23936023, 2013).
Constipation (1 paper, 2022). Infrequent or difficult evacuation of feces. "Furthermore, the network pharmacology analysis showed that Akt1, Stat3, Mapk8, Hsp90aa1, Cat, Alb, Icam1, Sod2, and Gsk3b can be regarded as the core anti-constipation targets." (PMID 35408632, 2022).
corneal disease (1 paper, 2021). "In this study, we evaluated the cytokine profiles of IL-2, IFN-γ, ICAM-1, IL-5, IL-6, IL-8, IL-10, IL-1β, MCP-1, IL-17A, IP-10, G-CSF, and VEGF-A in the AqH of BK patients before and after DMEK and in a control group without corneal disease." (PMID 34426617, 2021).
cutaneous leishmaniasis (1 paper, 2018). Leishmaniasis affecting the skin. "CLA-positive cells can use both VLA-4/VCAM-1 and LFA-1/ICAM-1 for extravasation on skin surfaces, which could account the enrichment of T cells expressing this receptor in the lesion of cutaneous leishmaniasis patients." (PMID 30662437, 2018).
cutaneous T-cell lymphoma (1 paper, 2025). "In follicular keratosis, when epidermal keratinocytes do not express ICAM-1, the expression of ICAM-1 is upregulated in the follicular epithelium adjacent to LFA-1-positive follicular cutaneous T-cell lymphoma cells." (PMID 40040698, 2025).
cysticercosis (1 paper, 2024). "Importantly, our study points to the potential influence of sex in modulating cytokine profiles in response to cysticercosis and HIV, with male sex being associated with decreased levels of IL-8, IL-17, IL-4, and ICAM-1, emphasizing a suppressive effect of male sex on these cytokines." (PMID 39093864, 2024).
deafness (1 paper, 2020). An inherited or acquired condition characterized by the complete loss of the ability to hear from one or both ears. "In noise-induced deafness, proinflammatory cytokines or chemokines, including TNF-α, IL-1β, IL-6, Icam-1, and Ccl2, were increased in cells of the stria vascularis or lateral wall." (PMID 33505961, 2020).
diabetic angiopathy (1 paper, 2013). "The results also provide experimental evidence of diabetic angiopathy, which is generated by ETD through increases in VCAM-1, ICAM-1 and P-selectin." (PMID 24499567, 2013).
enteritis (1 paper, 2010). Inflammation of the small intestine. "Furthermore, ICAM-1 mRNA was also down-regulated in MTX induced enteritis rat models and LPS treated IEC-6 cells after treated with curcumin." (PMID 20885979, 2010).
enteropathy (1 paper, 2012). "In summary, increased apoptosis and upregulation of ICAM-1 and HLA-DR expression in intestinal ECs from SIV infected RMs are suggestive of its role in SIV enteropathy." (PMID 22291924, 2012). "Early apoptosis and upregulation of ICAM-1 and HLA-DR in intestinal ECs are thought to be the key features in SIV mediated enteropathy." (PMID 22291924, 2012).
exophthalmos (1 paper, 2021). "A statistically significant difference in methylation status intercellular adhesion molecule 1 (ICAM1) between GD patients and controls was observed, and there was a significant association between decreased ICAM1 methylation and exophthalmos in GD patients." (PMID 35059400, 2021).
fascioliasis (1 paper, 2010). A parasitic infection that is caused by liver flukes, usually Fasciola hepatica, of sheep, goats, and cattle. "Soluble adhesion molecules namely soluble intercellular adhesion molecule-1 (sICAM-1) and soluble E-selection (sELAM-1) have been assayed in human fascioliasis cases with or without complications." (PMID 22347231, 2010).
fungal keratitis (1 paper, 2018). "The neutrophil infiltration and ICAM-1 expression were blocked by MC inhibitors during the early stage of fungal keratitis." (PMID 29849098, 2018).
galactosaemia (1 paper, 2018). "We studied two genes as possible anti-inflammatory markers, ANXA1 and ICAM1, the former which we previously reported as dysregulated in galactosaemia." (PMID 30231941, 2018). "The expression of ANXA1 and ICAM1 expression correlated strongly in galactosaemia patients (rs = 0.624, p < 0.05 × 10− 4), suggesting an inflammatory association." (PMID 30231941, 2018).
gastric diseases (1 paper, 2022). "ICAM-1 is significantly upregulated at sites of inflammation in H.pylori-stimulated gastric epithelial cells, indicating the important role of ICAM-1 in H.pylori-related gastric diseases." (PMID 35506423, 2022).
gastroschisis (1 paper, 2024). Gastroschisis is marked by viscera protruding, without a covering sac, from the fetal abdomen on the right lateral base of the umbilicus. "On the other hand, two California population-based case-control studies suggested that there were specific ICAM1 variants (ICAM1 gly241arg and ICAM1 rs281432) associated with an increased risk for gastroschisis." (PMID 39728087, 2024). "Another study in Indonesia analyzed the frequency of the ICAM1 common variant K469E in gastroschisis patients but was unable to demonstrate that ICAM1 K469E is a genetic risk for gastroschisis." (PMID 39728087, 2024). "Padula investigated 75 genetic variants in 20 genes and found 11 gastroschisis-associated variants in NOS3, ADD1, GNB3, ICAM1, ICAM4, ICAM5, and NAT1 genes." (PMID 39728087, 2024). "Besides ICAM1, the study from the Torfs group also identified a heterozygous/homozygous variant of NOS3, NPPA, ADD1, SERPINE1, and SELE, genes involved with cell–cell interactions, inflammation, or blood pressure, associated with gastroschisis." (PMID 39728087, 2024).
goiter (1 paper, 2023). Enlargement of the thyroid gland usually caused by lack of iodine in the diet, hyperthyroidism, or thyroid nodules. "Apical protein expression of ICAM-1 was positive in 52.5% (n = 21) of our goiter samples, 51.2% (n = 22) of FA samples, and 31.8% (n = 7) of FTC samples." (PMID 36906717, 2023).
head and neck squamous cell carcinoma (1 paper, 2023). A squamous cell carcinoma that arises from any of the following anatomic sites: lip and oral cavity, nasal cavity, paranasal sinuses, pharynx, larynx, and salivary glands. "IL-1β elicited ICAM1 expression by modulating intracellular ROS levels in head and neck squamous cell carcinoma, thereby fostering drug resistance." (PMID 37865637, 2023).
Heat Stroke (1 paper, 2025). A condition caused by the failure of body to dissipate heat in an excessively hot environment or during PHYSICAL EXERTION in a hot environment. "Previous studies have found that curcumin alleviates liver injury induced by heat stroke in a dose-dependent manner by down-regulating NF-κB, NOS2, and ICAM-1." (PMID 41430255, 2025).
hemophilia (1 paper, 2020). Hemophilia is a genetic disorder characterized by spontaneous hemorrhage or prolonged bleeding due to factor VIII or IX deficiency. "No clear differences were found in patients with severe hemophilia with and without acute joint bleeding for the serum markers endostatin, ferritin, ICAM-1, lactic acid, thrombomodulin (TM), VEGF and hemoglobin." (PMID 33023246, 2020).
hemorrhagic stroke (1 paper, 2018). A stroke caused by a bleed on the brain. "Results showed that the levels of ICAM1 and protein concentration increased and suggested that activated ICAM-1 increases gene expression for proteins and resulted in increased risk for ICAM associated clotting which may increase risk of ischemic and hemorrhagic stroke." (PMID 29867445, 2018).
Hodgkins lymphoma (1 paper, 2021). A heterogeneous group of malignant lymphoid neoplasms of B-cell origin characterized histologically by the presence of Hodgkin and Reed-Sternberg (HRS) cells in the vast majority of cases. "In addition, fucosylated ICAM1 was identified as a potential biomarker for distinguishing Hodgkin’s lymphoma from other lymphocytic cancers." (PMID 34199928, 2021).
Hydrocephalus (1 paper, 2025). Hydrocephalus is an active distension of the ventricular system of the brain resulting from inadequate passage of CSF from its point of production within the cerebral ventricles to its point of absorption into the systemic circulation. "aSAH patients demonstrated significantly higher levels of VCAM-1, ICAM-1, and SAA in the CSF for both timepoints when compared with hydrocephalus patient controls." (PMID 40427506, 2025). "We identified significant increases in vascular injury proteins (CRP, SAA, ICAM-1, and VCAM-1) at 5 days post-injury in the serum and CSF when compared to healthy, age-matched and unaffected (hydrocephalus) controls, respectively." (PMID 40427506, 2025).
hyperlipemia (1 paper, 2010). "Also, Liu et al4 reported that KK homozygotes had a higher risk of re-stenosis after coronary stenting and concluded that the ICAM-1 KK genotype may serve as a predictor of in-stent re-stenosis, especially in obese and hyperlipemia patients." (PMID 20940515, 2010).
hyperreactivity (1 paper, 2023). "IL-13 causes goblet cell metaplasia, bronchial hyperreactivity, and eosinophil extravasation by stimulating the expression of intercellular adhesion molecule 1 (ICAM-1) and vascular cell adhesion molecule 1 (VCAM-1)." (PMID 37569846, 2023).
hypertensive emergencies (1 paper, 2022). "Interestingly, the elevated expression of ICAM-1 was observed in cases of the hypertensive emergencies." (PMID 36247461, 2022).